GSDME (gasdermin E)
Diseases named in the same sentence as GSDME in open-access papers (continued):
Sharing a sentence is not in itself a finding about the gene and the disease.
breast carcinoma (89 papers, 2017 to 2025). "This methylation-induced silencing of GSDME has been linked to poor prognosis and lower survival rates in breast cancer patients." (PMID 39555415, 2024). "According to the results, a specific methylation of CpGs in GSDME promoter was identified associated with breast cancer." (PMID 38104141, 2023). "GSDME, capable of converting non-inflammatory apoptosis to pyroptosis, has been reported to trigger antitumor immunity, while reduced GSDME is associated with decreased breast cancer survival." (PMID 36267972, 2022). "The inactivation of GSDME conforms to the clinical and animal results that lower the expression of GSDME and is associated with a poor 5‐year survival and enhanced metastases in breast cancer." (PMID 34459122, 2021). "The estrogen receptor in breast cancer cell lines is inversely associated with GSDME methylation and expression." (PMID 34335940, 2021). "Ganoderma lucidum extract (GLE) has immunomodulatory, anti-inflammatory and anti-angiogenic effects in cancer therapy, and studies have shown that GLE in breast cancer activates caspase-3 to cleave the GSDME protein and release inflammatory factors to cause an immune response." (PMID 37542283, 2023). "Additionally, in breast cancer patients, the methylation status of GSDME was linked to lymph node metastases." (PMID 36119049, 2022). "Reduced GSDME expression is associated with decreased breast cancer survival, suggesting that GSDME might be a tumor suppressor in breast cancer." (PMID 35659304, 2022). "In addition, the study suggests that high GSDME methylation in breast cancer patients is linked to lymph node metastasis, therefore, breast cancer patients with the risk of lymph node metastasis can be identified by GSDME." (PMID 35462927, 2022). "GSDME downregulation is associated with shorter survival of patients with breast cancer." (PMID 35896522, 2022). "Moreover, in breast cancer, a decrease in the levels of GSDME is associated with a decrease in survival rate." (PMID 34553845, 2022). "GSDME was originally identified as a tumor suppressor because its expression was downregulated in breast cancer and reduced GSDME was associated with poor survival of breast cancer patients." (PMID 34925465, 2021). "This suggests that the neoplastic characteristics of breast cancer cells might be due in part to the loss of GSDME expression." (PMID 34490348, 2021). "GSDME has been reported to be suppressed in the expression of a variety of cancer cells, and low expression of GSDME was found to be associated with a better prognosis in breast cancer; thus, GSDME may be a tumour suppressor." (PMID 38652105, 2024). "Additionally, in breast cancer, the decrease in GSDME levels is associated with a decrease in the survival rate, indicating that GSDME may be a tumor suppressor." (PMID 34553845, 2022). "Accelerated progression via the cleavage of GSDME has been observed in various breast cancer cells, but, in general, it does appear to be quite cell-line specific." (PMID 40331965, 2025). "Collectively, these findings demonstrated that 2-DG activates the cAMP/PKA pathway to suppress HK2 expression, thereby triggering caspase-3/GSDME-mediated pyroptosis in mouse breast cancer cells." (PMID 41415273, 2025). "Collectively, these findings demonstrated that GSDME is critical for mediating 2-DG-induced pyroptosis in murine breast cancer cells." (PMID 41415273, 2025). "Due to promoter hypermethylation, GSDME is epigenetically silenced in most solid tumors, including gastric, colorectal, and breast cancers." (PMID 40568597, 2025). "Mitoxantrone 14, a fused polycyclic aryl compound, induces pyroptosis in breast cancer cells through the activation of caspase-1 and caspase-3, leading to GSDME activation." (PMID 39316325, 2025).
breast carcinoma (continued). "This study extends this mechanistic landscape by defining a novel pathway in murine breast cancer cells, in which 2-DG elicits caspase-3/GSDME-dependent pyroptosis." (PMID 41415273, 2025). "For instance, in breast cancer, GSDME has activated DOX-induced pyroptosis in the caspase-3-dependent reactions through the ROS/JNK signaling pathway." (PMID 38172670, 2024). "Demethylating agents like Decitabine (DAC) has also been shown to upregulate GSDME expression in breast cancer." (PMID 39575419, 2024). "Multiple studies have shown that in a wide range of estrogen receptor-positive (ER+) breast cancer cell lines, the level of GSDME expression is often low, indicating its possible role as a decisive factor in hormone-unresponsive breast cancer." (PMID 38169676, 2024). "Decreased GSDME expression in LPS and ATP-treated tumor cells confirmed the existing data illustrating the down-regulation of GSDME in breast cancer conditions." (PMID 39433537, 2024). "Some studies have shown that GSDME is epigenetically silenced in several cancers, such as gastric cancer, colorectal cancer and breast cancer, and is considered a tumor suppressor gene." (PMID 36605484, 2023). "Trimethylamine N-oxide (TMAO) can induce GSDME-mediated pyroptosis in breast cancer cells, and TMAO in combination with PD-1 can increase the antitumor activity of PD-1 alone." (PMID 36605484, 2023). "Recently, researchers have found that, in breast cancer, the GSDME expression level is increased and caspase-8 can cleave GSDME, triggering pyroptosis and increasing DCs, CD4+ and CD8+ T cells." (PMID 37705746, 2023). "Nevertheless, researchers have explored the re-expression of GSDME as a potential strategy to induce pyroptosis in breast cancer cells." (PMID 38066523, 2023). "As in other cancers, GSDME is substantially downregulated in breast cancer and inhibits cell proliferation and invasion." (PMID 37752941, 2023). "GSDME is the core of pyroptosis and plays a significant role in breast cancer cells, which has a great potential to suppress the tumor growth and metastasis." (PMID 37125240, 2023). "In this study, we aimed to explore the role of GSDME methylation in the sensitivity of chemotherapy for breast cancer." (PMID 36867605, 2023). "In mouse models of colon and breast cancer, tubulysin, a microtubule depolymerizing agent, can trigger tumor cell death by targeting the GSDME-mediated pyroptotic pathway and modulating tumor sensitivity to ADC treatment." (PMID 38104141, 2023). "As a typical anthracycline antitumor drug, doxorubicin can induce ROS accumulation, JNK phosphorylation and ultimately promote pyroptosis through the caspase-3/GSDME pathway in breast cancer cells." (PMID 38016064, 2023). "In other words, the combined treatment of decitabine and Taxol resulted in the upregulation of GSDME expression in breast cancer resistant cells, which induced pyroptosis and made the cells more sensitive to chemotherapy drugs." (PMID 36867605, 2023). "Recent findings indicate that metformin activates AMPK/SIRT1 signaling, promotes NF-κB expression, and induces caspase-3/GSDME-mediated pyroptosis in various cancer cells, including hepatoblastoma, colon cancer, and breast cancer cells." (PMID 38066523, 2023). "As reported, GSDME expression was frequently epigenetic silenced by methylation in several cancers, including breast cancers." (PMID 36823153, 2023).
breast carcinoma (continued). "Tetraarsenic hexoxide is a chemotherapeutic agent for clinically advanced cancer patients that increases ROS production and GSDME-mediated pyroptosis and inhibits invasive metastasis of breast cancer cells." (PMID 37542283, 2023). "The ROS accumulation caused by adriamycin (DOX) treatment in HER2-positive breast cancer tissues causes the phosphorylation of JNK and the caspase-3 cleavage of GSDME-induced pyroptosis." (PMID 37542283, 2023). "To determine the extent to which GSDME expression increased before and after the treatment of decitabine treatment, we performed qPCR and WB analyses on three groups of breast cancer cells." (PMID 36867605, 2023). "GSDME promoter methylation was highly correlated with lymph node metastasis in breast cancer, and overexpression of GSDME in colon cancer cell lines significantly reduced the growth and colony-forming ability of these cells." (PMID 37679782, 2023). "Studies have found that the expression level of GSDME is one of the key factors affecting the chemosensitivity of breast cancer cells." (PMID 36867605, 2023). "Further analysis of survival data from breast cancer patients revealed an intimate correlation between GSDME methylation and 5-year overall survival (OS), suggesting that GSDME methylation has potential as a prognostic biomarker." (PMID 35462927, 2022). "Due to promoter hypermethylation, GSDME expression is downregulated in breast cancer, gastric cancer, oesophageal cancer, and colorectal cancer." (PMID 35480866, 2022). "A recent study reported by Yaqiong Li indicated that breast cancer cells undergo pyroptosis via the AIM2/caspase-3/GSDME pathway active by DHA." (PMID 36119049, 2022). "In the mouse colon cancer cell line CT-26 and the mouse breast cancer cell line 4 T-1 with reduced GSDME expression, GSDME expression was significantly increased after decitabine intervention." (PMID 35480866, 2022). "In breast cancer, the Gasdermin E (GSDME) expression level has a close correlation to the ER status." (PMID 35739182, 2022). "GSDMD and GSDME, two essential pyroptosis substrates, play significant roles in the etiology and pathogenesis of breast cancer." (PMID 36119049, 2022). "An experiment conducted by Lei Hu proved that breast cancer cells were stimulated to undergo pyroptosis via BAK or BAX/caspase-3/GSDME axis with the treatment of TNFα+CHX and navitoclax." (PMID 36119049, 2022). "GSDME is another pore forming molecule which is activated in caspase‐3‐mediated pyroptosis, and its methylation is a potential biomarker in breast cancer." (PMID 35574984, 2022). "A recent study reported that DRD2 can regulate the tumor microenvironment and facilitate M1 polarization of macrophages and activated GSDME-executed pyroptosis in breast cancer." (PMID 35712671, 2022). "Nevertheless, the GSDME cleavage was induced and increased by 4f in both breast cancer cell lines in a dose-depended manner." (PMID 35551332, 2022). "Recently, Yaqiong Li found that DHA inhibited tumorigenesis by inducing AIM2/caspase-3/GSDME regulated pyroptosis in breast cancer cells." (PMID 36119049, 2022). "For instance, GSDME methylation at high frequency contributed to lymph node metastasis and a poor prognosis for breast cancer patients." (PMID 36936274, 2022). "We demonstrated that GSDME deficiency facilitated breast cancer cell proliferation and colony formation while CDK7 inhibition impaired the ability of breast cancer proliferation and colony formation." (PMID 34490348, 2021). "Here, we consistently demonstrated that GSDME downregulation facilitated breast cancer cell growth and colony formation." (PMID 34490348, 2021). "On the other hand, DOX‐activated ROS affects the cleavage of Caspase‐8; the c‐Caspase‐8 would promote the cleavage of Caspase‐3, the c‐Caspase‐3 will induce the cleavage of GSDME, and triggered pyroptosis of breast cancer cells." (PMID 34369076, 2021).
breast carcinoma (continued). "We also demonstrated that the GSDME deletion contributed to breast cancer cell proliferation and colony formation." (PMID 34490348, 2021). "These outcomes suggest that low expression of GSDME is required for both cell proliferation and colony formation of breast cancer cells." (PMID 34490348, 2021). "GSDME expression was markedly decreased in human breast cancer and colon adenocarcinoma tissues compared with matched tumor-adjacent tissues mainly attributing to its hypermethylation." (PMID 33634141, 2021). "This discovery suggested GSDMB as a novel for the evaluation and prognosis of breast cancer while another study, the known out of GSDME strongly inhibited PTX‐induced pyroptosis in MCF‐7 breast cancer cell." (PMID 34369076, 2021). "Overall, these findings suggest that triclabendazole promotes pyroptosis in breast cancer cells, representing a promising drug candidate for breast cancer therapy for patients with higher expression of GSDME." (PMID 34305590, 2021). "We performed western blotting to detect the GSDME protein levels in multiple breast cancer cell lines." (PMID 34490348, 2021). "The highest GSDME cleavage observed in DOX treated cells asserted that DOX induces pyroptosis in breast cancer cells via a Caspase‐GSDME pathway." (PMID 34369076, 2021). "But the human breast cancer line MCF‐7 and mouse mammary carcinoma cell line EMT6 have been found to express high levels of GSDME." (PMID 32437063, 2020). "For instance, upregulation of GSDMD in lung cancer or GSDMC in colorectal cancer correlates with poor prognosis and therapeutic resistance, whereas reactivation of GSDME in breast cancer or AIM2 in gastric cancer has been shown to re-sensitize tumors to chemotherapy and inhibit proliferation." (PMID 41291696, 2025). "Also, numidargistat 25 is reported as a pyroptotic agent against breast cancer and various other cancers by activating GSDME, caspase-1, and caspase-3/GSDMD." (PMID 39316325, 2025). "Recently, doxorubicin was shown to induce pyroptosis through gasdermin E in breast cancer cells." (PMID 41225536, 2025). "At the same time, the release of DAMPs, HMGB1 and ATP, were detected, suggesting that GSDME may mediate paclitaxel-induced pyroptosis in breast cancer cells through the caspase-9/caspase-3 pathway." (PMID 38954046, 2024). "Paclitaxel-treated MDA-MB-231 cells showed GSDME cleavage, suggesting that paclitaxel may induce pyroptosis in breast cancer cells with high GSDME expression." (PMID 38954046, 2024). "It was found that paclitaxel and doxorubicin, an anthracycline, could induce typical pyroptosis and bubbling in breast cancer cells, accompanied by gasdermin E (GSDME) cleavage." (PMID 38954046, 2024). "The high expression of GSDME was also observed in breast cancer MCF-7 cells." (PMID 38902235, 2024). "Our findings may help to better understand the molecular mechanisms of resistance in breast cancer and suggest that GSDME overexpression is a promising strategy to combat multidrug resistance." (PMID 36867605, 2023). "Therefore, overexpression of endogenous GSDME in breast cancer is expected to simultaneously activate pyroptosis and promote immune cell infiltration, thus effectively suppressing tumor growth." (PMID 36823153, 2023). "The expression level of GSDME in breast cancer cells was observed by qPCR and WB analyses." (PMID 36867605, 2023).
breast carcinoma (continued). "NI‐TA is a photocatalytic superoxide radical generator, which could trigger pyroptosis in MDA‐MB‐231 breast cancer via a caspase‐3/GSDME pathway for excellent stemness inhibition and tumor growth suppression." (PMID 37125240, 2023). "GSDME methylation is a promising biomarker for the diagnosis and prognosis of breast cancer." (PMID 37752941, 2023). "Recent studies have suggested that GSDME may play several important roles in the early diagnosis of breast cancer." (PMID 36867605, 2023). "In addition, a positive correlation was found between lymph node metastasis and the degree of GSDME methylation, suggesting that breast cancer patients with higher GSDME methylation levels are more likely to experience lymph node metastasis." (PMID 38104141, 2023). "Demethylation of cells increased the expression of GSDME in breast cancer-resistant cells." (PMID 36867605, 2023). "We aim to test the feasibility of regulating the expression of GSDME may be an effective method to improve the breast cancer chemotherapy effect and reduce drug resistance." (PMID 36867605, 2023). "Therefore, we can use the DNA methyltransferase inhibitor—decitabine to increase the expression of GSDME in certain cancer cells (such as gastric cancer, colorectal cancer, breast cancer, etc.)to increase the sensitivity of its to chemotherapy drugs." (PMID 36867605, 2023). "However the GSDME is regulated by methylation in breast cancer, which heavily limits the induction of pyroptosis by chemotherapeutic drugs through GSDME protein cleavage." (PMID 36823153, 2023). "Similarly, another study also analyzed the GSDME promoter methylation in a larger number of breast cancer samples and proposed that GSDME methylation was a potential biomarker for breast cancer diagnosis." (PMID 36823153, 2023). "Triclabendazole could induce GSDME‐dependent pyroptosis through caspase‐3 activation, which shows a good potential for breast cancer therapy." (PMID 37125240, 2023). "GSDME expression varies in different breast cancer cell lines." (PMID 35896522, 2022). "Several studies have shown that the pyroptosis core genes behave differently in different tumors, with GSDMC, GSDMD, and GSDMB acting as oncogenes in colorectal cancer, small-cell lung cancer, and breast cancer, respectively, while GSDME acts as a tumor suppressor in a variety of cancers." (PMID 35769504, 2022). "Methylated GSDME could increase the risk of lymph node metastasis in breast cancer 41, indicating anti-tumor potentials of GSDME in the regulation of breast cancer." (PMID 35541900, 2022). "GSDME expression was silenced in colorectal, gastric, and breast cancer, indicating that GSDME may be a tumour suppressor gene." (PMID 35620407, 2022). "Further study on the regulation of GSDME in breast cancer was still in tremendous potential." (PMID 35541900, 2022). "Thus, the right chemotherapy agents for the therapeutics of breast cancer should be chosen based on levels of GSDME expression to enhance the sensitivity to chemotherapy medications and reduce drug resistance." (PMID 36119049, 2022). "To verify which Gasdermin protein could be involved in drug pyroptosis‐induced in breast cancer cells, we assessed the protein expression of GSDME and GSDMD by Western blotting." (PMID 34369076, 2021). "In summary, we found that all chemotherapy drugs may lead to pyroptosis and GSDME cleavage in breast cancer cells." (PMID 34369076, 2021). "Similar to GSDMD, GSDME expression was also decreased in GC, as well as in breast cancer and CRC." (PMID 34429144, 2021). "Methylation analysis shows that in breast cancer and colorectal cancer, the hypermethylated promoter of GSDME was relevant to patients’ prognosis, suggesting that GSDME methylation could be a potential detection and prognostic marker." (PMID 34298833, 2021).